RN7SL479P (RNA, 7SL, cytoplasmic 479, pseudogene)
Gene: Miscellaneous RNA gene on chromosome 1 (44,117,098 to 44,117,397, reverse strand). Ensembl gene ENSG00000239560.
Homologues: Orthologues: chimpanzee Metazoa_SRP (99% identical), macaque Metazoa_SRP (95% identical). Paralogues in human: RN7SL1 (83% identical), RN7SL2 (83% identical), RN7SL3 (83% identical), RN7SL45P (82% identical), RN7SL786P (81% identical), RN7SL113P (80% identical), RN7SL118P (80% identical), RN7SL126P (80% identical), RN7SL187P (80% identical), RN7SL278P (80% identical), RN7SL30P (80% identical), RN7SL47P (80% identical), and 702 more.